YTHDF2 (YTH N6-methyladenosine RNA binding protein F2)
Diseases named in the same sentence as YTHDF2 in open-access papers (continued):
Sharing a sentence is not in itself a finding about the gene and the disease.
rheumatoid arthritis (7 papers, 2020 to 2025). A chronic, systemic autoimmune disorder characterized by inflammation in the synovial membranes and articular surfaces. "For example, FTO, ALKBH5 and YTHDF2 have been described as risk factors for rheumatoid arthritis." (PMID 41009809, 2025). "For example, global m6A and METTL3 expression levels have been shown to be significantly increased, while FTO, ALKBH5 and YTHDF2 mRNA levels have been shown to be significantly downregulated in rheumatoid arthritis (RA)." (PMID 36457997, 2022). "This study examined YTHDF2's role in modulating IL‐6R signaling to regulate synovial fibroblast inflammation and bone damage in rheumatoid arthritis (RA)." (PMID 40548546, 2025). "However, little is known about the role of ALKBH5, FTO, and YTHDF2 in rheumatoid arthritis (RA)." (PMID 32884942, 2020). "Likewise, m6A levels in rheumatoid arthritis (RA) patients’ and ischemic stroke patients’ blood were elevated relative to healthy controls, along with decreased ‘eraser’ ALKBH5 and FTO levels and increased YTHDF2 ‘reader’ levels in RA samples." (PMID 36831575, 2023).
thyroid cancer (7 papers, 2020 to 2024). "We analyzed the expression of 17 m6A-related genes in thyroid cancer and adjacent tissues and found that except for YTHDF2, the other 16 genes were differentially expressed in thyroid cancer." (PMID 36389678, 2022). "Analyses of TCGA database revealed that most of m6A RNA methylated regulators except YTHDF2 were dysregulated in thyroid carcinoma, suggesting that m6A RNA modification plays a critical role in thyroid cancer development." (PMID 34281544, 2021). "This revealed that YTHDF2 was up-regulated between thyroid carcinoma tissues and normal tissues." (PMID 39593172, 2024). "Similarly, in thyroid cancer, METTL3-regulated m6A modification enhances STTEAP1 mRNA stability in a YTHDF2-dependent manner, thereby inhibiting thyroid cancer cell proliferation, migration, and invasion." (PMID 38576024, 2024). "On the contrary, the expression of YTHDF2 was lower in renal tumors including kidney chromophobe carcinoma (KICH) and renal papillary cell carcinoma (KIRP), brain lower grade glioma (LGG) and thyroid carcinoma (THCA), than that in the adjacent non-tumorous tissues." (PMID 36120577, 2022).
esophageal squamous cell carcinoma (6 papers, 2022 to 2024). Esophageal squamous cell carcinoma (ESCC) is a type of esophageal carcinoma (EC) that can affect any part of the esophagus, but is usually located in the upper or middle third. "In addition, Linc00022 can be inhibited by the m6A reader, YTHDF2, to influence the invasion and proliferation of esophageal squamous cell carcinoma." (PMID 35692827, 2022). "Research demonstrated that increased FTO in esophageal squamous cell carcinoma (ESCC) lowered the m6A methylation of LINC00022 transcripts, causing LINC000222 degradation to be repressed by YTHDF2." (PMID 38125749, 2023). "For examples, FTO can decrease m6A methylation of LINC00022 transcript, contributing to the suppression of LINC00022 decay via the m6A reader YTHDF2 in esophageal squamous cell carcinoma (ESCC), thereby promoting the cell proliferation and tumor growth of ESCC." (PMID 34787056, 2022).
diffuse large B-cell lymphoma (5 papers, 2020 to 2025). "High YTHDF2 expression promotes diffuse large B‐cell lymphoma (DLBCL) cell proliferation and supports tumor growth by inhibiting apoptosis." (PMID 39802639, 2025). "YTHDF2 also promotes the progression of diffuse large B-cell lymphoma by regulating alkaline ceramidase 2-mediated ceramide metabolism in an m6A-dependent manner." (PMID 39593172, 2024). "Similarly, YTHDF2 promotes diffuse large B-cell lymphoma (DLBCL) progression by modulating ACER2-mediated ceramide metabolism in an m6A-dependent manner." (PMID 40332203, 2025).
endometriosis (5 papers, 2023 to 2025). The growth of functional endometrial tissue in anatomic sites outside the uterine body. "One study reported that METTL3 and YTHDF2 were identified as potential diagnostic targets for endometriosis, suggesting the importance of the METTL3-m6A-mRNA/long non-coding RNA (lncRNA)-YTHDF2 axis in the development of endometriosis." (PMID 37891533, 2023). "We constructed a diagnostic m6A signature of endometriosis and found that METTL3 and YTHDF2 might be the key m6A targets of EM through experiments." (PMID 36675186, 2023). "Zhang reported that m6A alterations may be key factors in the progression of endometriosis, particularly the significant downregulation of METTL3 and YTHDF2 expression." (PMID 40000966, 2025). "For example, the first investigation into how m6A regulators function in endometriosis indicated that m6A regulators in endometriosis, such as METTL3, YTHDF2, YTHDF3, HNRNPC, HNRNPA2B1, and FTO, are significantly dysregulated compared with normal endometrial tissue." (PMID 36894952, 2023). "Finally, we found that m6A alterations might be one of the important reasons for the progression of endometriosis, especially with significant downregulation of the expressions of METTL3 and YTHDF2." (PMID 36675186, 2023).
head and neck squamous cell carcinoma (5 papers, 2020 to 2022). A squamous cell carcinoma that arises from any of the following anatomic sites: lip and oral cavity, nasal cavity, paranasal sinuses, pharynx, larynx, and salivary glands. "However, YTHDF2 expression was lower in head and neck squamous cell carcinoma, KICH (kidney chromophobe), KIRC (kidney renal clear cell carcinoma), kidney renal papillary cell carcinoma, and LIHC (liver hepatocellular carcinoma) tissues than in adjacent normal tissues." (PMID 32986017, 2020).
heart failure (5 papers, 2021 to 2024). Inability of the heart to pump blood at an adequate rate to meet tissue metabolic requirements. "In the cardiovascular field, Ythdf2 was increased in heart failure with preserved ejection fraction (HFpEF) patients, compared with healthy controls." (PMID 35383152, 2022). "This study highlights the functional importance of YTHDF2-dependent cardiac m6A mRNA regulation during heart failure, and sheds light on potential new targets for hypertrophy and HF therapy." (PMID 34266473, 2021). "Our study highlights the functional importance of YTHDF2-dependent cardiac m6A mRNA regulation during heart failure, and provides a novel mechanistic insight into the therapeutic mechanisms of YTHDF2." (PMID 34266473, 2021). "Since BHPF-induced downregulation of YTHDF2 is the key event for induction of ferroptosis-dependent heart failure, we examined whether BHPF-mediated CVP defects are also driven by the same pathway." (PMID 38152479, 2023). "In heart failure, certain proteins, such as YT521-B homology domain family 2 (YTHDF2), are notably upregulated, as observed in tissues affected by human heart failure and hypertrophic mouse hearts." (PMID 39334823, 2024). "Ythdf2 knockdown also led to CVP defects, suggesting that the CVP phenotype may correlate with ferroptosis and heart failure." (PMID 38152479, 2023). "In heart failure mouse model constructed by transverse aortic constriction (TAC) surgery and primary cardiomyocytes stimulated with ISO model, researchers found that the mRNA and protein level of Ythdf2 was remarkably increased during HF development." (PMID 35383152, 2022).
neuroblastoma (5 papers, 2021 to 2026). Neuroblastoma (NB) is the most common solid, extracranial childhood tumor. "This is evident in mouse neuroblastoma cells, where the loss of Fmrp is associated with reduced m6A‐modified transcripts, while knockdown of Ythdf2 leads to increased stability and longer half lives of modified RNAs." (PMID 39887636, 2025). "False-positive report probability analysis for significant findings for the association between YTHDF2 rs3738067 A>G polymorphism and neuroblastoma susceptibility." (PMID 34970571, 2021). "Our work for the first time verified the significant correlation of YTHDF2 gene rs3738067 A>G polymorphism with neuroblastoma risk, and this polymorphism is an intriguing locus for in-depth researches." (PMID 34970571, 2021). "Our study evaluated the association of the YTHDF2 gene SNP (rs3738067 A>G) with neuroblastoma susceptibility." (PMID 34970571, 2021). "Here, we estimated the association between a YTHDF2 gene rs3738067 A>G polymorphism and neuroblastoma susceptibility in 898 neuroblastoma patients and 1,734 healthy individuals from China." (PMID 34970571, 2021). "We carried out a multi-center epidemiology study among Chinese children to analyze the association between the SNPs in the key m6A modification modulator gene YTHDF2 and neuroblastoma susceptibility." (PMID 34970571, 2021). "After that, we assessed the relation between YTHDF2 gene polymorphism and neuroblastoma susceptibility in subgroups classified via age, gender, sites of origins as well as clinical stages." (PMID 34970571, 2021). "YTHDF2 rs3738067 A>G polymorphism and neuroblastoma susceptibility." (PMID 34970571, 2021). "Stratify analysis for YTHDF2 rs3738067 A>G polymorphism and neuroblastoma susceptibility." (PMID 34970571, 2021). "The present work verified the YTHDF2 rs3738067 A>G could reduce neuroblastoma risk for the first time." (PMID 34970571, 2021). "The genotyping of YTHDF2 was successfully screened in 896 neuroblastoma patients and 1,733 controls." (PMID 34970571, 2021). "However, the role of YTHDF2 in neuroblastoma remains largely unknown." (PMID 34970571, 2021).
renal cell carcinoma (5 papers, 2019 to 2025). "The findings of this study indicated that the m6A eraser ALKBH5 upregulated MANF in a YTHDF2-dependent fashion, thereby conferring protection against ER stress-induced cell death in renal cell carcinoma." (PMID 40603319, 2025). "In renal cell carcinoma (RCC), circPOLR2A, regulated by YTHDF2 through m6A modification, enhances the interaction between PEBP1 and UBE3C." (PMID 39075555, 2024). "However, in the tissues of renal cell carcinoma (RCC), METTL14 regulates the expression of NEAT1 through another recognition protein YTHDF2." (PMID 38654314, 2024). "Additionally, in NONO-TFE3 translocation renal cell carcinoma (NONO-TFE3 tRCC), a subtype of RCC associated with Xp11.2 translocation/TFE3 gene fusions RCC (Xp11.2 tRCCs), YTHDF2 played a tumor-suppressive role by suppressing poly(ADP-ribose) polymerase 1 (PARP1) expression." (PMID 38503745, 2024).
testicular germ cell tumor (5 papers, 2020 to 2023). A germ cell tumor arising from the testis. "Our results illustrated that FDX1 expression was positively correlated with YTHDF2 and TRMT10C expression in most cancers, except LIHC and testicular germ cell tumors (TGCT)." (PMID 36210836, 2022). "Some studies have shown that METTL3, ALKBH5, YTHDC1, YTHDF1, YTHDF2, and HNRNPC are the main m6A-related genes in type II testicular germ cell tumors." (PMID 32258108, 2020).
colon adenocarcinoma (4 papers, 2020 to 2024). "YTHDF2 expression also varied with tumors and was a risk factor in prostate adenocarcinoma (PRAD), KICH, THCA and LIHC, and a protective factor in colon adenocarcinoma (COAD), bladder urothelial carcinoma (BLCA), LUAD, KIRC and READ." (PMID 37833468, 2023).
diabetes (4 papers, 2023 to 2025). "Numerous studies have reported the involvement of N6-methyladenosine modification proteins, particularly YTHDF2, in modulating diabetes and its associated complications." (PMID 40785592, 2025). "Histone lactylation upregulates FTO expression, which controls CDK2 mRNA in an m6A-YTH domain-containing family protein 2 (YTHDF2)-dependent manner, promoting angiogenesis and triggering microvascular leakage in diabetes mellitus." (PMID 40584617, 2025). "Consequently, targeting YTHDF2 represents a potential therapeutic strategy for mitigating diabetes-induced liver damage." (PMID 40785592, 2025).
endometrioid endometrial carcinoma (4 papers, 2021 to 2023). "Some studies have shown that there is an interaction between RNA methylation and lncRNA in tumors, and m6A reader YTHDF2-mediated degradation of lncRNA FENDRR promoted cell proliferation in endometrioid endometrial carcinoma." (PMID 34917609, 2021). "For example, m6A reader YTHDF2-modified lncRNA FENDER degradation significantly promoted endometrioid endometrial carcinoma cell proliferation." (PMID 34336856, 2021). "In endometrioid endometrial carcinoma (EEC) cells, YTHDF2 mediates FENDRR degradation promoting tumor cell proliferation." (PMID 37438359, 2023).
lymph node metastasis (4 papers, 2020 to 2022). "YTHDF2 was significantly associated with certain clinicopathological characteristics, such as lymph node metastasis, vascular invasion and tumour node metastasis (TNM) stage." (PMID 35696608, 2022). "The expression of METTL3, METTL14, WTAP, YTHDC2, YTHDF1, and YTHDF2 was remarkably higher in CRPC with lymph node metastasis than in CRPC with bone metastasis, whereas ALKBH5, FTO, and YTHDF3 were substantially decreased in CRPC with lymph node metastasis." (PMID 33403026, 2021). "Subgroup analysis based on sample type, age, lymph node metastasis status, and disease stage showed that the level of YTHDF2 transcription in KIRC patients was substantially lower than that in healthy individuals." (PMID 34512342, 2021). "METTL3, YTHDC2, YTHDF1, and YTHDF2 had a remarkably high expression in PCa and CRPC with lymph node metastasis." (PMID 33403026, 2021). "Low-level expression of YTHDF2 had poor prognosis in ccRCC patients with lower tumor–node–metastasis (TNM) stage, age > 61, non-distant metastasis, non-lymph node metastasis, female gender, and higher histological grade (P < 0.05)." (PMID 33102202, 2020). "The present study found that decreased YTHDF2 expression had poor OS in ccRCC patients with lower TNM stage, higher age, non-distant metastasis, non-lymph node metastasis, female gender, and higher histological grade." (PMID 33102202, 2020).
asthma (3 papers, 2023 to 2025). "This mechanistic link is supported by earlier findings (see Section 5.1), where WTAP-mediated m6A modification of AXIN1 mRNA promotes its YTHDF2-dependent degradation, thereby enhancing Wnt/β-catenin signaling and contributing to airway smooth muscle cell proliferation in asthma." (PMID 41008562, 2025). "This proposes that the YTHDF2–WTAP–AXIN1 axis plays a pivotal role in regulating ASMC growth and offers potential therapeutic targets for asthma treatment." (PMID 41008562, 2025).
brain tumor (3 papers, 2021 to 2023). "We next examined the expression of YTHDF2 across three distinct public brain tumor datasets (Gravendeel, TCGA, and Rembrandt)." (PMID 36973285, 2023). "Our data on GBM inhibition by ablation of YTHDF2 demonstrated the potential of targeting YTHDF2 for therapeutic intervention of the life-threatening brain tumor." (PMID 33420027, 2021). "Taken together, this study reveals the importance of targeting YTHDF2 in combination with DC-immunotherapy to enhance the efficacy of ICB therapy against early stage brain tumors." (PMID 34571899, 2021). "Depletion of LXRα and HIVEP2 largely abolished tumor growth inhibition by YTHDF2 knockdown and drove the brain tumors more invasive as compared to those of YTHDF2 knockdown." (PMID 33420027, 2021). "The mice injected with GSC11- or GSC7-2-control cells all developed brain tumors resembling human GBM, whereas depletion of YTHDF2 substantially inhibited brain tumor formation." (PMID 33420027, 2021).
Burkitt lymphoma (3 papers, 2019 to 2024). A rare form of malignant mature B-cell non-Hodgkin lymphoma. "To further confirm this observation, we also established WT and RRR mutant YTHDF2-expressing cell lines using EBV-positive P3HR1 Burkitt lymphoma cells." (PMID 38236021, 2024). "YTHDF2 has been shown to promote or suppress KSHV lytic replication in a cell type-dependent manner but mainly to inhibit EBV replication in Burkitt lymphoma cells." (PMID 34425696, 2021). "We transduced Akata (EBV+) Burkitt lymphoma cells with these constructs, establishing stable cell lines expressing either WT or RRR mutant YTHDF2." (PMID 38236021, 2024).
female infertility (3 papers, 2017 to 2025). Diminished or absent ability of a female to achieve conception. "It is worth noting that YTHDF2 deficiency resulted in female infertility, preweaning lethality, and male hypo-fertile in mice." (PMID 40092485, 2025). "In detail, the deficiency of YTHDF2 led to female infertility, as YTHDF2 was essentially needed for oocyte competence and regulated transcript dosage post-transcriptionally during oocyte maturation." (PMID 33593354, 2021). "The female infertility in Ythdf2−/− mice could arise from either germline- or somatic-related defects." (PMID 28867294, 2017).
glaucoma (3 papers, 2022 to 2025). Increased pressure in the eyeball due to obstruction of the outflow of aqueous humor. "Our findings in this study suggest that YTHDF2 and its neuroprotective target mRNAs might be valuable in developing novel therapeutic approaches to treat neurodegeneration caused by glaucoma and other retinal injuries." (PMID 35179492, 2022). "By proteomic analysis and anti‐YTHDF2 RNA immunoprecipitation sequencing, we have identified Hspa12a and Islr2 as the YTHDF2 targets in a glaucoma model." (PMID 40371666, 2025). "Loss of function of YTHDF2 results in increased RGC dendrite branching, more synapses, improved visual acuity, and more resistance for glaucoma model." (PMID 40371666, 2025). "In an acute intraocular pressure elevation (AOH)-induced glaucoma model, RGCs from YTHDF2 cKO mice showed greater resistance to injury, reduced dendritic atrophy, and less neuronal loss." (PMID 41315216, 2025). "In the glaucoma models, the m6A writers METTL3 and WTAP, and its reader YTHDF2, are upregulated, and the loss‐of‐function of YTHDF2 has a neuroprotective role." (PMID 40371666, 2025). "While certain m6A-related genes, such as METTL3 and YTHDF2, have been identified as regulated in glaucoma models, it remains unclear whether the m6A modification pattern is consistent across all patients or universally applicable across different ethnic groups and individuals." (PMID 41315216, 2025). "YTHDF2 also mediates acute ocular hypertension (AOH)-induced RGC degeneration, the experiment model for glaucoma, and Ythdf2 cKO in the retina alleviates AOH-induced RGC dendrite shrinking and neuronal loss." (PMID 35179492, 2022).
hepatoblastoma (3 papers, 2021 to 2024). Hepatoblastoma (HB) is a malignant hepatic tumor and is the most common pediatric liver cancer. "Indeed, mutations in the YTHDF2 were linked to the lower expression of BIRC7 and NK4IN4 in human hepatoblastoma, and genetic duplication of GMBE1 and YTHDF2 was noted in cases of human megalencephaly, suggesting them as candidate genes for this disease." (PMID 39596561, 2024). "While high level of METTL3 or YTHDF2 can be used as the poor prognostic factor for hepatoblastoma." (PMID 33708621, 2021). "YTHDF2 is significantly overexpressed in hepatoblastoma and HCC when compared with their adjacent non-cancerous tissues, and overexpression of YTHDF2 is closely connected with poor prognostic clinical outcomes." (PMID 34616742, 2021).
kidney chromophobe (3 papers, 2020 to 2022). "In kidney renal clear cell carcinoma (KIRC), kidney chromophobe (KICH), kidney renal papillary cell carcinoma (KIRP), YTHDF2 expression in cancer tissues was lower than that in adjacent normal tissues." (PMID 34512342, 2021).
multiple myeloma (3 papers, 2024). "YTHDF2 was identified to promote multiple myeloma cell proliferation via STAT5A/MAP2K2/p-ERK axis." (PMID 37256443, 2024). "A previous study showed that YTHDF2 can recognize STAT5A and mediate its degradation in multiple myeloma." (PMID 38879589, 2024). "It has been reported that YTHDF2 recognizes m6A-modified STAT5A and promotes its mRNA degradation in multiple myeloma." (PMID 38879589, 2024).